HMOX1 (heme oxygenase 1)
Diseases named in the same sentence as HMOX1 in open-access papers (continued):
Sharing a sentence is not in itself a finding about the gene and the disease.
cancer (continued). "Targeting the Nrf2/Heme oxygenase-1 pathway can significantly increase oxidative stress in RCC and promote apoptosis and death of cancer cells, while Heme oxygenase-1 has a dual role in ferroptosis induction." (PMID 39399506, 2024). "Heme oxygenase-1 (HMOX1) is involved in the cytoprotection, promote cancer metastasis while different drugs including erastrin reverses its resistance by ferroptosis." (PMID 38633616, 2024). "For instance, GSTO2 and PGF were down-regulated while CSF1R, DDB2, HMOX1 and PGFB were up-regulated in both cancers." (PMID 38790250, 2024). "Our regression modeling of cancer mRNA expression data from over 11,000 patients in the TCGA PANCAN database suggested that heme exposure, measured by HMOX1 expression, strongly predicts SPP1." (PMID 38060331, 2023). "The results showed that compared with normal cells (N), the NLRP3, EDN1, HMOX1, and CXCL1 genes were upregulated in the cancer cell group (T)." (PMID 36118079, 2022). "The dysregulation of significant cancer-related genes (FAM83H, CXCL12, PITPNA, HMOX1, DGKZ, NR5A2, VMP1, and ID1) was confirmed by qRT-PCR." (PMID 36232920, 2022). "While PRSS8 has clearly been shown to promote apoptosis in multiple cancer contexts through regulation of several relevant proteins (PTEN, Bax, and MMP9), the role of HMOX1 in regulating apoptosis appears to vary across tissues." (PMID 36457077, 2022). "The heme oxygenase 1 gene (HMOX1) reduces oxidative stress and exerts diverse functions in cancer cells." (PMID 36232920, 2022). "For example, the strong induction of heme oxygenase-1 (HO-1), one of the Nrf2/ARE downstream antioxidant/detoxifying enzymes, favors tumorigenesis and cancer progression." (PMID 35453311, 2022). "In nucleus, NRF2 forms a heterodimer with sMaf and binds to ARE, protecting cancer cells from GPX4 inhibition and promoting the transcription of antioxidant enzymes, such as HMOX1, NOQ1, and GSTS, reducing ROS levels, forming resistance to ferroptosis." (PMID 36505465, 2022). "Moving forward, we focused on HMOX1 and PRSS8, which have been shown previously to regulate cell survival in various cancer contexts." (PMID 36457077, 2022). "Positively correlations were observed between HMOX1 expression and regulatory T cells (Tregs), activated CD4+ memory T cells, as well as M2 macrophages in most cancer types." (PMID 34858984, 2021). "We previously reported that hnRNPK regulates the proliferation of cancer cells by targeting polo-like kinase 1 (PLK1) and heme oxygenase-1 (HO-1)." (PMID 33731671, 2021). "The fasting-mimicking diet selectivity reverses vitamin C-induced up-regulation of heme-oxygenase-1 and ferritin in KRAS-mutant cancer cells, consequently increasing reactive iron, oxygen species, and cell death; an effect further potentiated by chemotherapy." (PMID 32393788, 2020). "In cancer cells, in addition to PUMA and BAX, PpIX induced the expression of heme oxygenase HMOX-1, a stress response gene." (PMID 30886745, 2019). "When exposed to paclitaxel, cancer cells activated the EIF2AK3/EIF2AK4‐pEIF2S1‐ATF4 axis and maintained redox homoeostasis by inducing expression of the major antioxidant enzymes HMOX1, SHMT2 and SLC7A11." (PMID 31211507, 2019). "Doxorubicin (Dox)-induced cardiotoxicity, a limiting factor in the use of Dox to treat cancer, can be mitigated by the mitogenic factor FGF2 in vitro, via a heme oxygenase 1 (HO-1)-dependent pathway." (PMID 30159756, 2018). "We demonstrated that ME1 knockdown increased the expression of HMOX-1 (HO-1), which is an oxidative stress marker regulated by Nrf2,18 suggesting that ME1 depletion disturbs metabolic and redox balance in cancer cells." (PMID 28481367, 2017).
cancer (continued). "The transcription factor Nrf2 binds to antioxidant responsive elements at the promoters of its target genes, such as HMOX1 and NQO1, to activate antioxidant gene expression, and renders cancer cells resistant to oxidative stress-mediated cell death." (PMID 27764794, 2016). "Nrf2 and its target genes (e.g., heme oxygenase-1 (HO-1)], NAD(P)H:quinone oxidoreductase 1 (NQO-1), and sulfiredoxin-1 (Srx1)) protect not only normal cells but also cancer cells from oxidative stress." (PMID 26904167, 2016). "Specifically, significant decreases in expression of HMOX1 (−50-fold, p = 0.03) and aldolase (ALDOA; −500-fold, p = 0.01) were observed in CD49fhiCD24hi cancer cells compared with benign cell counterparts." (PMID 26316122, 2015). "Consistent with a role for NFE2L2 in vitamin D-mediated cancer prevention, a number of NFE2L2 target genes were increased in RWPE1 cells after 1,25(OH)2D treatment, e.g. GPX3, HMOX1, AKR1C2, and TXNRD1." (PMID 20070897, 2010). "Here we demonstrate a novel pathway involving FLIPL negatively regulating the expression of heme oxygenase-1 (HO-1), whose role in chemoresistance, both in AML and other cancers, is well established." (PMID 21307400, 2010). "Besides, it is important to bear in mind that HMOX1 and NQO1 are also two of the genes related to the main pathway deregulated by Ocoxin in all the four analyzed cancers: cell metabolism." (PMID 40176904, 2025). "Some non-cancer studies proved that H2 treatment induced a significant increase in the expression of intracellular SOD, GPx, CAT, and heme oxygenase-1 (HO-1), enhancing their potential to eliminate ROS." (PMID 38555538, 2024). "By inducing the transcription of hypoxic inducible factor (HIF), hypoxia triggers many signaling cascades responsible for cancer progression and aggressiveness, including enhanced expression of vascular endothelial growth factor (VEGF) or antioxidant enzymes, such as heme oxygenase-1 (HO-1)." (PMID 38791428, 2024). "In addition, we predicted the sensitivity of common anti-cancer drugs on prognostic signature, including CCR5, HMOX1, CTSC, CD5, BCL3, CDH1, TYROBP and CD38." (PMID 38767825, 2024). "In these hemorrhagic regions, we found an increased Cd68 signal, confirming macrophage infiltration, superimposed by upregulated expression of Hmox1 and Arg1, the latter of which is the archetypal marker for procancerous and immunosuppressive TAMs in mice, similar to CD163 and SPP1 in human cancers." (PMID 38060331, 2023). "In addition, we found that macrophage subpopulations (clusters 1, 5, 7, 8, and 9) from cancer tissues expressed a certain number of immunosuppressive genes, such as VEGFA, MMP14, MMP19, S100A2, APOE, HMOX1, SLAMF7, SIRPα, LAG3 and IL18." (PMID 36158683, 2022). "HMOX1, ARRB1, and PDIA3 were significantly differentially expressed in LUAD-normal and LUAD-cancer." (PMID 35957802, 2022). "Its high expression may increase the metastasis ability of cancer cells of NSCLC patients, and HMOX1 has the potential as a therapeutic target for NSCLC in the future." (PMID 35957802, 2022). "Heme oxygenase-1 (HMOX-1), a phase II enzyme that responds to electrophilic stimuli, has been reported to play protective or detrimental effects in different diseases, including cancers." (PMID 35422048, 2022). "Furthermore, this flavonol inhibits xanthine oxidase (XO) activity and increases the activities of catalase, heme oxygenase‐1 (HO), and superoxide dismutase (SOD) in a wide range of cancer and non‐cancer cells." (PMID 36259115, 2022). "In cancer cells, heme oxygenase-1 (HMOX1/HO-1) may improve cancer aggressiveness and resistance to therapy, resulting in poor prognosis." (PMID 36510497, 2022).
cancer (continued). "Heme oxygenase-1 (HMOX1, HO-1) was a potential target for human cancers." (PMID 34858984, 2021). "Protein expressions of HMOX1, HSPB1 and NCOA4 were markedly decreased in cancer tissues." (PMID 33996565, 2021). "Meanwhile, c-JUN, HMOX1, and CTGF play an oncogenic role in cancer." (PMID 33579362, 2021). "Dysregulation of HMOX1 was relevant to ARS-CoV-2 and cancer." (PMID 35127768, 2021). "The expression of HMOX1 is upregulated in different types of cancer, but its role in cancer or UM has not been elucidated." (PMID 33540700, 2021). "Of note, we have previously shown that SLV-11199 does not induce HMOX1 expression, in other cancer cell lines, such as pancreatic PANC-1 or prostate DU-145 cells." (PMID 31963199, 2020). "Indeed, evidence has been obtained in cancer cells that Nrf2 may directly regulate the expression of HIF1A, the gene encoding HIF-1α, while in cardiomyocytes HIF-1α upregulation has been reported to be related to Nrf2 activation through heme oxygenase-1 (HO-1) expression." (PMID 32545222, 2020). "Moreover, TUS was proven to regulate cancer cell proliferation, angiogenesis, and inflammation via Wnt, VEGFR2, and Irf and heme oxygenase-1 (HO-1) pathways, respectively." (PMID 32317967, 2020). "Heme oxygenese 1 enzyme (HO1 coded by HMOX1 gene), similar to NRF2 in normal homeostasis, exhibits antioxidant effects, while over-expression has been observed in different types of cancer changes." (PMID 29247444, 2018). "It has been shown that curcumin activated NRF2 in several cell types and exerted a cytoprotective effect through transcriptional induction of phase II enzymes, such as glutathione transferase, NQO1, HMOX-1, GCLC, and GCLM in certain human cancers, skin lesions, and neurodegenerative diseases." (PMID 23710286, 2013). "Under hypoxic condition HIF-1 coordinates the expression of many genes that orchestrate angiogenesis and cancer cell metabolism reprogramming, including GLUT1 and GLUT3, glycolytic enzymes, vascular endothelial growth factor (VEGF), erythropoietin (EPO), heme oxygenase-1 (HO-1), etc." (PMID 23144690, 2012). "Heme oxygenase-1 expression has been reported to enhance growth against apoptosis and induce angiogenesis through increase in angiogenic factor and VEGF in endothelial cells and cancer cells." (PMID 15365571, 2004). "Thus, the overexpression of HMOX1 and NQO1 observed in cancer cells treated with Ocoxin could have accounted for the subsequent mortality of those cells when exposed to the compound." (PMID 40176904, 2025). "HMOX1 was identified as a strong positive predictor for both TAM markers, suggesting that intratumoral heme exposure due to microhemorrhage may be a critical factor in fostering cancer-promoting TAMs." (PMID 38060331, 2023). "Because METTL7B enhanced the expression of essential ROS-scavenging enzymes, SOD1, GPX4 and HMOX1 as well as their enzymatic activities, it is worthy to explore whether METTL7B could promote resistance to other anti-cancer reagents in addition to TKIs in the future." (PMID 35144642, 2022). "Through NRF2 activation, DMF modulates the expression of a variety of anti-oxidant enzymes, including heme oxygenase 1 (HO-1) and NADPH dehydrogenase (quinone 1) (NQO1), thus dysregulating the intracellular radical oxygen species (ROS) level, whose fine balance is required for cancer cell survival." (PMID 35743211, 2022). "In summary, among the prognostic genes we screened, the potential relationship amongBIRC5, HMOX1, and VEGFA in HCC prognosis had been reported previously, while VPS35might be a newly identified oncogene of HCC, and further, VPS26A and PRKCD were alsofound to have roles related to cancer." (PMID 33351066, 2021). "Also WA regulates the activity of antioxidant enzymes (such as superoxide dismutase) and mRNA expression of antioxidant genes: erythroid 2-like 2 (NFE2L2), heme oxygenase 1 (HMOX1), glutathione-disulfide reductase (GSR), and NAD(P)H quinone dehydrogenase 1 (NQO1)) in cancer cells." (PMID 33498013, 2021).
cancer (continued). "Although HMOX1 expression is upregulated in the process of ferroptosis in cancer cells, it is not clear whether HMOX1 is induced in this context to enhance ferroptosis or as a protective response." (PMID 34692692, 2021). "Other genes such as HMOX1 were the targets of eight non-anti-cancer non-FDA-approved drugs." (PMID 30842898, 2019). "Hmox1 can stimulate angiogenesis and is prometastatic in some but not all cancers." (PMID 27999449, 2016). "Furthermore, other botanicals like Curcuma longa and Ginkgo biloba exert anti-cancer effects primarily through apoptosis or autophagy pathways, and the C. nitidissima leaf extract induces ferroptosis in NSCLC cells by modulating intracellular ROS, MDA, and GSH levels and upregulating HMOX-1." (PMID 40573219, 2025). "The Cancer Genome Atlas (TCGA) and Gene Expression Omnibus (GEO) datasets also revealed that the HMOX1 mRNA level (HO-1) is lower in patients with head and neck squamous carcinoma (HNSCC) and NPC than in patients without cancer." (PMID 35682782, 2022). "Phase 2 genes are upregulated during oxidative stress, members include heme oxygenase 1 (HO-1), glutathione S-transferase (GST), and NADP-quinone reductase and therefore have been explored as possible cancer therapeutic targets." (PMID 34439409, 2021). "Heme oxygenase 1 (HMOX1) and biliverdin reductase (BLVRA) are key enzymes in heme catabolism and bilirubin formation, whose systemic concentrations have a direct and negative relationship on the prevalence of cancer." (PMID 30057678, 2018).
infection (275 papers, 2009 to 2026). The state of being infected such as from the introduction of a foreign agent such as serum, vaccine, antigenic substance or organism. "or bacterial infections, HMOX1 was induced by the infection with L. infantum in both sexes, which is associated with pathogen survival within the macrophage." (PMID 40794782, 2025). "In a previous review of HMOX1 polymorphisms and infection, we showed that this classification was inconsistent and that misclassification creates a significant risk of bias." (PMID 37414746, 2024). "As much in-vitro and in-vivo work suggests there is a link between HMOX1 activity and outcomes in infection, we aimed to systematically review the literature on the HMOX1 GT(n) repeat polymorphism and outcomes in infection." (PMID 35551540, 2022). "Although there are now 15 studies in human infection that have aimed to assess the impact of the GT(n) repeat polymorphisms in HMOX1, the clinical data remains sparse and difficult to interpret." (PMID 35551540, 2022). "In particular, HMOX1 has antiviral activity with increased levels associated with clearance of infection." (PMID 34358063, 2021). "As observed in Nrf2-/- mice, dKO mice presented greater ROS levels at week 6 post-infection and less expression of NRF2-target genes Hmox1 and Nqo1 as measured at week 3 post-infection on total footpad lesions caused by LgyLRV1+ parasites." (PMID 33765083, 2021). "NF-κB target genes (i.e., C3, Chi3l1, Fas, Gadd45β, Hmox1, Ptx3, Saa3, Tlr2) were also abundant in DEGs in which upregulation during infection was impaired by CCR5-deficiency." (PMID 31506064, 2019). "Upregulation of Hmox1 during infection with T. gondii was also impaired by CCR5-deficiency at 30 dpi." (PMID 31506064, 2019). "Murine models of infection coupled with a deficiency in heme oxygenase-1 (HO-1), a key enzyme of heme catabolism, suggest that the release of heme following hemolysis increases mortality." (PMID 24691127, 2014). "Heme may increase host susceptibility to infection by inducing heme oxygenase 1 (HMOX-1) in immature neutrophils, thereby inhibiting the oxidative burst required to clear phagocytic bacteria." (PMID 36937929, 2023). "With this approach, large (>10,000) cohorts with detailed clinical phenotyping may be able to be genotyped for this repeat, which should provide further clarity on the role of HMOX1 promoter polymorphisms in infection." (PMID 35551540, 2022). "Mechanistically, scavenging ROS with NAC inhibited BCG-induced macrophage ferroptosis and the release of BCG into the culture medium caused by necroptosis/ferroptosis during the infection, while siRNA-mediated knockdown of Hmox1 gene expression resulted in opposite effects to NAC treatments." (PMID 36211962, 2022). "Despite the importance of HMOX1 in survival from infection, and the association between repeat length and gene expression, the clinical data supporting an association between repeat length and incidence and/or outcome of infection remain inconclusive." (PMID 35551540, 2022). "In addition, NF-κB target genes (i.e., C3, Chi3l1, Fas, Gadd45β, Hmox1, Ptx3, Saa3, Tlr2) were abundant in the DEGs in which upregulation during infection was impaired by CCR5-deficiency." (PMID 31506064, 2019). "Heme oxygenase-1 (HO-1), an inducible enzyme involved in heme degradation, has been demonstrated to play a crucial role in the host's response to Plasmodium infection." (PMID 41836435, 2026). "Hemin treatment reduced the parasite load, supporting the role of HMOX1 activity in controlling Tg infection." (PMID 41379884, 2025). "THP-1 cells were pre-treated with either vehicle, arbutin, the HMOX1 inducer and activator hemin, or a combination of arbutin and hemin, followed by infection with Tg RH." (PMID 41379884, 2025). "In the case of VL, upon infection, there is a marked upregulation of the antioxidant enzyme heme oxygenase-1 (HO-1)." (PMID 40538050, 2025).